FKBP11 (FKBP prolyl isomerase 11)
Description:
PPIases accelerate the folding of proteins during protein synthesis.
Synonyms: FKBP19
Tractability: Small molecule: it belongs to a druggable protein family. Antibody: UniProt predicts a signal peptide or a membrane-spanning region. PROTAC: ubiquitination databases record sites on it; its protein half-life has been measured.
Gene: Protein-coding gene on chromosome 12 (48,921,518 to 48,926,474, reverse strand). Ensembl gene ENSG00000134285.
Subcellular location: Membrane
Subcellular location (Human Protein Atlas): Centrosome
Gene Ontology:
Molecular function: peptidyl-prolyl cis-trans isomerase activity
Cellular component: membrane
Genetic constraint (gnomAD): Loss-of-function variants: 21 observed, 25.45 expected, observed/expected ratio (o/e) 0.83, 90% interval 0.58 to 1.19. The upper end of that interval is the gene's LOEUF score, 1.19, which puts it in group 5 of 6, group 1 being the genes least tolerant of losing a copy. Missense variants: 245 observed, 259.72 expected, observed/expected ratio (o/e) 0.94, 90% interval 0.85 to 1.05. Synonymous variants: 106 observed, 104.69 expected, observed/expected ratio (o/e) 1.01, 90% interval 0.86 to 1.19.
Homologues: Orthologues: chimpanzee FKBP11 (100% identical), guinea pig FKBP11 (92% identical), dog FKBP11 (91% identical), mouse Fkbp11 (91% identical), pig FKBP11 (62% identical), tropical clawed frog fkbp11 (61% identical), zebrafish fkbp11 (48% identical), Caenorhabditis elegans fkb-5 (21% identical), Caenorhabditis elegans fkb-4 (18% identical). Paralogues in human: FKBP10 (28% identical), FKBP2 (27% identical), FKBP9 (25% identical), FKBP15 (24% identical), FKBP4 (22% identical), FKBP7 (22% identical), FKBP3 (22% identical), FKBP5 (21% identical), FKBP14 (20% identical), FKBP8 (19% identical), FKBP1C (19% identical), FKBP1A (18% identical), and 6 more.
Diseases named in the same sentence as FKBP11 in open-access papers:
FKBP11 is named in the same sentence as 30 diseases in open-access papers, as found by Europe PMC text mining. Sharing a sentence is not in itself a finding about the gene and the disease. The quoted sentences say what the papers report.
hepatocellular carcinoma (4 papers, 2020 to 2023). A malignant tumor that arises from hepatocytes. "When treating patients with clear cell renal cell carcinoma, NDUFV3 was found to be an independent predictor of overall survival, whereas FKBP11 has the potential to be an early marker for hepatocellular carcinoma." (PMID 36999050, 2023). "In addition, a gradual increase in FKBP11 expression has been detected in the development of hepatocellular carcinoma (HCC), suggesting that FKBP11 may be a potential early biomarker for HCC." (PMID 33425993, 2020). "FKBP11 expression progressively increases during the development of hepatocellular carcinoma (HCC)." (PMID 37014329, 2023).
melanoma (4 papers, 2016 to 2023). A malignant, usually aggressive tumor composed of atypical, neoplastic melanocytes. "Whereas the role of TNC (tenascin C) and FN1 (fibronectin 1) in melanoma development is well documented, implication of MARCKS, RCN3, BAMBI, PEA3/ETV4 and the FK506 family members FKBP7, FKBP10 and FKBP11 in melanoma progression is unclear." (PMID 27689402, 2016). "The results suggested that FKBP11 may be a potential early marker of HCC; the expression of FKBP11 is also increased in melanoma, but the exact mechanism of action is unclear." (PMID 37014329, 2023).
osteosarcoma (3 papers, 2023 to 2024). A usually aggressive malignant bone-forming mesenchymal neoplasm, predominantly affecting adolescents and young adults. "In conclusion, the potential prognostic factor associated with patient survival, FKBP11, can predict the prognosis of osteosarcoma patients based on its effect on the development of osteosarcoma." (PMID 37014329, 2023). "We detected the expression of FKBP11 in osteosarcoma by qRT-PCR, western blotting, and immunohistochemistry and performed CCK-8, Transwell, colony formation, and flow cytometry assays to reveal the regulatory role of FKBP11." (PMID 37014329, 2023). "Then, we assessed proliferation, invasion, migration, and colony formation in osteosarcoma cells upon FKBP11 silencing." (PMID 37014329, 2023). "We found that FKBP11 was highly expressed in osteosarcoma; silencing FKBP11 expression suppressed the invasion and migration of osteosarcoma cells, slowed cell proliferation, and promoted apoptosis." (PMID 37014329, 2023). "The immunohistochemistry results showed that the expression of FKBP11 in osteosarcoma tissues was higher than that in para-cancerous tissues." (PMID 37014329, 2023). "Our experiments validated the role of FKBP11 in the development of osteosarcoma at the tissue and cellular levels." (PMID 37014329, 2023). "The results clearly showed that the mRNA and protein levels of FKBP11 were higher in osteosarcoma cells than in HFOB1.19 osteoblasts." (PMID 37014329, 2023). "In our study, we confirmed that the development of osteosarcoma is regulated by the prognostic factor FKBP11." (PMID 37014329, 2023). "More interestingly, the expression of several of these genes, including CHST13, FKBP11, SGMS2, TRPS1, PRKX, SP7, and DNAJC1, were highly associated with osteosarcoma prognosis." (PMID 37457661, 2023). "Next, we further examined the effect of FKBP11 in regulating osteosarcoma cell apoptosis." (PMID 37014329, 2023). "We further assessed the expression of FKBP11 in osteosarcoma tissues." (PMID 37014329, 2023). "Our findings revealed the value of FKBP11 in predicting osteosarcoma patient prognosis." (PMID 37014329, 2023). "We then explored whether FKBP11 plays a tumor-promoting role in osteosarcoma through the MAPK pathway." (PMID 37014329, 2023). "Moreover, we found that the knockdown of FKBP11 inhibited the MAPK signaling pathway, suggesting that FKBP11 may promote the development of osteosarcoma via the MAPK pathway." (PMID 37014329, 2023). "Furthermore, FKBP11 was found to play a cancer-promoting role in osteosarcoma by vitro assays." (PMID 37014329, 2023). "To further analyze the expression of FKBP11 in osteosarcoma, we compared the expression of FKBP11 in HFOB1.19 cells and osteosarcoma cells by using qRT-PCR and western blotting." (PMID 37014329, 2023). "After silencing FKBP11 in MG63 and 143B cells, the proliferation of osteosarcoma cells was significantly suppressed according to the results of the CCK-8 assay." (PMID 37014329, 2023). "In addition, when FKBP11 was silenced in MG63 and 143B cells, osteosarcoma cells had decreased migratory and invasive abilities." (PMID 37014329, 2023). "Additionally, we identified a novel mechanism by which FKBP11 ameliorates the malignant properties of osteosarcoma cells through the MAPK pathway and serves as a prognostic factor in osteosarcoma." (PMID 37014329, 2023).
systemic lupus erythematosus (3 papers, 2015 to 2022). An autoimmune multi-organ disease typically associated with vasculopathy and autoantibody production. "Notably, FKBP11 is overexpressed in B-cells of patients suffering from Systemic Lupus Erythematosus, a chronic inflammatory autoimmune disease." (PMID 35456020, 2022). "Also, FKBP11 expression in peripheral B cells from Systemic Lupus Erythematosus (SLE) patients, a severe and prototypic autoimmune disease, has been found to correlate with increased numbers of peripheral plasmablasts." (PMID 35456020, 2022). "FKBP11 is involved in the regulation of mTOR and the pathogenesis of stress-related inflammatory diseases, including type 2 diabetes mellitus, systemic lupus erythematosus, and hepatitis." (PMID 33425993, 2020).
autoimmune disease (2 papers, 2022 to 2023). A disorder resulting from loss of function or tissue destruction of an organ or multiple organs, arising from humoral or cellular immune responses of the individual to their own tissue constituents. "While FKBP10, FKBP11 (this study), and FKBP2 have been reported in the context of IPF, others have demonstrated a role of FKBP11 in autoimmune disease." (PMID 35456020, 2022). "Although CD is a heterogeneous autoimmune disease, the expression levels of five key genes (TNF, BIRC3, ANXA1, TNIP3, and FKBP11) were significantly higher in most CD tissues than that in normal tissues." (PMID 37047025, 2023).
cardiac hypertrophy (2 papers, 2019 to 2021). "FKBP11 was strongly and acutely induced in cardiac hypertrophy induced by TAC." (PMID 34054926, 2021).
Crohn disease (2 papers, 2024 to 2025). A gastrointestinal disorder characterized by chronic inflammation involving all layers of the intestinal wall, noncaseating granulomas affecting the intestinal wall and regional lymph nodes, and transmural fibrosis. "Highly expressed FKBP11 is involved in the pathogenesis of auto-inflammatory diseases including SLE and Crohn’s disease." (PMID 41153404, 2025).
lymphoma (2 papers, 2015 to 2022). A malignant (clonal) proliferation of B- lymphocytes or T- lymphocytes which involves the lymph nodes, bone marrow and/or extranodal sites. "Notably, our findings are backed up by previous transcriptomic studies on UPR-induced gene expression in the lymphoma cell line Raji and in fibroblasts, which also show upregulation of FKBP11 transcript." (PMID 35456020, 2022).
asthma (1 paper, 2026). "Differentially methylated loci were near genes related to asthma (ITPR2, MAPK1), lung function (FKBP11), mitochondrial function (MRPL20, SPTBN1), inflammation (C3), and immune function (N4BP3, EIF5)." (PMID 41749276, 2026).
Autoimmunity (1 paper, 2015). The occurrence of an immune reaction against the organism's own cells or tissues. "The higher expression of FKBP11 mRNAs in these cells, compared to control B cells, led us to study the effects of FKBP11 overexpression on B cell phenotype and on the development of autoimmunity." (PMID 26417441, 2015). "To understand the consequences of FKBP11 overexpression on B cell function and on autoimmunity's development, we created lentiviral transgenic mice reproducing this gene expression variation." (PMID 26417441, 2015). "In order to understand the possible consequences of FKBP11 overexpression on B cell function and autoimmunity, we developed a functional genomic approach consisting in the production and analysis of a new lentigenic mouse model overexpressing Fkbp11, on C57BL/6 background." (PMID 26417441, 2015). "Furthermore, the overexpression of Fkbp11 exacerbated some features of autoimmunity in the B6lpr/lpr model." (PMID 26417441, 2015). "The role of FKBP11 in B cells and in autoimmunity has never been described." (PMID 26417441, 2015).
Burkitt lymphoma (1 paper, 2022). A rare form of malignant mature B-cell non-Hodgkin lymphoma. "We therefore assessed, using treatment with the ER stress inducer tunicamycin and subcellular fractionation, whether FKBP11 localized to the ER and was upregulated by ER stress in the B lymphocyte cell line Raji (derived from Burkitt’s lymphoma) and in A549 cells (derived from lung adenocarcinoma)." (PMID 35456020, 2022).
dissection (1 paper, 2017). The separation and isolation of tissues for surgical purposes, or for the analysis or study of their structures. "Taken together that the current study involving both WGCNA and complementary gene expression analysis identify FKBP11 is a key player in aortic dissection." (PMID 29255427, 2017).
glioma (1 paper, 2019). A benign or malignant brain and spinal cord tumor that arises from glial cells (astrocytes, oligodendrocytes, ependymal cells). "AS of KIF4A and AS of FKBP11 were hub events in this network with important splicing predictors of glioma prognosis." (PMID 31729991, 2019).
myeloma (1 paper, 2022). "While we, after multiple rounds of optimization, succeeded to achieve an acceptable and consistent knockdown efficiency for both FKBP11 and PPIB in the hybridoma cell line, we failed doing so for the plasma cell myeloma cell line JK-6L." (PMID 35456020, 2022).
renal carcinoma (1 paper, 2023). A carcinoma arising from the epithelium of the renal parenchyma or the renal pelvis. "FKBP11 expression is strongly correlated with advanced disease and poor prognosis in patients with renal cancer, and can promote cell proliferation and tumorigenesis." (PMID 38188020, 2023).
skin cancer (1 paper, 2016). "FKBP7, FKBP11 and FKBP10, upregulated 3.21, 2.42 and 15.18-fold, respectively, have not yet been described in skin cancer." (PMID 27689402, 2016).
tumor (6 papers, 2021 to 2025). "Immune infiltration analysis revealed significant associations between the four genes (BASP1, CCL8, FCGR1B, FKBP11) used for risk stratification and tumor microenvironment composition in KIRC." (PMID 40909125, 2025). "Among them, ANXA1 and FKBP11 were highly expressed in tumor tissues compared to normal tissues, whereas BIRC3 and TNIP3 were lowly expressed in tumor tissues." (PMID 37047025, 2023). "The results of our experiments suggested that FKBP10 and FKBP11 might play important roles in the maintenance of the tumor characteristics of ccRCC." (PMID 34476212, 2021). "qRT-PCR results showed that the expression of FKBP10 and FKBP11 was increased in tumor tissue." (PMID 34476212, 2021). "The results showed that FKBP10 and FKBP11 have a low degree of methylation in tumor tissues." (PMID 34476212, 2021). "FKBP11, a member of the FK506-binding protein family, has been implicated in various cellular processes, including protein folding and stress response, which may contribute to its role in tumor progression." (PMID 40151638, 2025). "The analysis revealed significantly higher expression levels of BASP1, FCGR1B, and FKBP11 in KIRC compared to normal adjacent tissues, while CCL8 showed no significant differential expression between tumor and non-tumor tissues." (PMID 40909125, 2025). "FKBP11, PHF19, ARPC3, and MS4A14 were overexpressed in tumor tissues." (PMID 35651604, 2022).
cancer (4 papers, 2018 to 2025). A tumor composed of atypical neoplastic, often pleomorphic cells that invade other tissues. "In all the three GC datasets, the positive regulation of PPP1R1B by XBP1 was increased from normal to cancer, and the negative regulation of FKBP11 by XBP1 was strengthened." (PMID 29745833, 2018). "All these genes (AP2M1, FKBP11, GALNT6, BDNF, COL9A3 and NR4A1) favor relevant features of cancer progression, indicating that their epigenetic activation in CTCs of CRC patients under treatment could be a key event for the development of therapy resistance and cancer progression." (PMID 38188020, 2023).
FKBP11 also shares sentences with these, for which no sentence is quoted: diabetes (2 papers); Aortic dissection (1); clear cell renal cell carcinoma (1); heart failure (1); Hepatitis (1); lung adenocarcinoma (1); lung carcinoma (1); lung fibrosis (1); neuroblastoma (1); oral cancer (1); prostate carcinoma (1); type 2 diabetes mellitus (1).